SLIT3 (slit guidance ligand 3)
Description:
May act as molecular guidance cue in cellular migration, and function may be mediated by interaction with roundabout homolog receptors.
Synonyms: Slit-3; MEGF5; SLIL2; slit2; SLIT1
Tractability: Antibody: UniProt places it where antibodies can reach, with medium confidence; UniProt predicts a signal peptide or a membrane-spanning region; its Gene Ontology location is reachable by antibodies, with medium confidence. PROTAC: its protein half-life has been measured.
Gene: Protein-coding gene on chromosome 5 (168,661,740 to 169,301,139, reverse strand). Ensembl gene ENSG00000184347.
Subcellular location: Secreted
Subcellular location (Human Protein Atlas): Cell Junctions; Predicted to be secreted
Pathways (Reactome):
Developmental Biology: Netrin-1 signaling; Regulation of commissural axon pathfinding by SLIT and ROBO; Signaling by ROBO receptors
Gene Ontology:
Molecular function: Roundabout binding; calcium ion binding; heparin binding
Biological process: apoptotic process involved in luteolysis; axon extension involved in axon guidance; axon guidance; cellular response to hormone stimulus; chemorepulsion involved in embryonic olfactory bulb interneuron precursor migration; negative chemotaxis; negative regulation of cell growth; negative regulation of chemokine-mediated signaling pathway; response to cortisol; Roundabout signaling pathway; aortic valve morphogenesis; atrioventricular valve morphogenesis; ventricular septum morphogenesis
Cellular component: cell junction; extracellular region; mitochondrion; non-collagenous component of interstitial matrix
Genetic constraint (gnomAD): Loss-of-function variants: 63 observed, 163.35 expected, observed/expected ratio (o/e) 0.39, 90% interval 0.31 to 0.48. The upper end of that interval is the gene's LOEUF score, 0.48, which puts it in group 2 of 6, group 1 being the genes least tolerant of losing a copy. Missense variants: 1,632 observed, 1,931.7 expected, observed/expected ratio (o/e) 0.84, 90% interval 0.81 to 0.88. Synonymous variants: 800 observed, 788.27 expected, observed/expected ratio (o/e) 1.01, 90% interval 0.96 to 1.08.
Homologues: Orthologues: macaque SLIT3 (98% identical), rabbit SLIT3 (95% identical), chimpanzee SLIT3 (95% identical), dog SLIT3 (94% identical), pig SLIT3 (94% identical), guinea pig SLIT3 (94% identical), mouse Slit3 (94% identical), rat Slit3 (94% identical), tropical clawed frog slit3 (80% identical), zebrafish slit3 (69% identical). Paralogues in human: SLIT2 (67% identical), SLIT1 (60% identical), TLR9 (11% identical), LRFN1 (11% identical), SLITRK5 (11% identical), LRFN5 (10% identical), SLITRK3 (10% identical), LRRN2 (10% identical), SLITRK2 (10% identical), LRFN3 (10% identical), LRRN1 (10% identical), LRFN2 (9% identical), and 13 more.
Diseases named in the same sentence as SLIT3 in open-access papers:
SLIT3 is named in the same sentence as 90 diseases in open-access papers, as found by Europe PMC text mining. Sharing a sentence is not in itself a finding about the gene and the disease. The quoted sentences say what the papers report.
breast carcinoma (13 papers, 2004 to 2025). "SLIT3 is widely expressed in human tissues and its deregulation has been associated with cancer, including breast cancer." (PMID 31766143, 2019). "In breast cancer cell lines, hypermethylation caused silenced SLIT3, which was re‐activated after treating with 5‐aza‐2′‐deoxycytidine Moreover, re‐activation of SLIT3 inhibited the growth and migration of breast cancer cell lines; thereby, it appeared to function as a novel cancer suppressor gene." (PMID 40778650, 2025). "The KM analysis, along with the typical IHC staining of SLIT3, TNN, IGHD, and KRRB1, showed that the expression was significantly different between normal and breast cancer tissues and confirmed the prognostic effect of the TME risk signature." (PMID 36059555, 2022). "The chemokine-mediated signaling pathway is represented by SLIT2 and SLIT3 genes that play a suppressive role in tumor metastasis and are often epigenetically silenced in a wide variety of cancers including breast cancer." (PMID 32679794, 2020). "miR-218 is located within the introns of SLIT2 and SLIT3, whose promoter regions are frequently hypermethylated in cancers, including ovarian cancer, breast cancer, and cervical cancer." (PMID 26610476, 2015). "In addition, SLIT3 was identified as an active ligand secreted from CD36+ FBs that induced growth suppression of MDA-MB-231 breast cancer cells." (PMID 36752296, 2023). "Then, we identified SLIT3, FBLN-1, and PENK as active protein ligands secreted from CD36+ FBs that induced growth suppression of MDA-MB-231 breast cancer cells and determined their minimum effective concentrations." (PMID 36361532, 2022). "For instance, transcription factor SOX17 (SOX17), slit guidance ligand 3 (SLIT3), and cysteine dioxygenase type 1 (CDO1) that are frequently suppressed by hypermethylation in breast cancer, turned hypomethylated after resveratrol treatment." (PMID 27355345, 2016). "The expressions of PCDH12, SLIT3, ACVRL1 and DLL4 not merely relate to the type and proportion of immune cells, but also contribute to the prognosis of breast cancer." (PMID 35953532, 2022).
lung carcinoma (12 papers, 2004 to 2025). "In conclusion, SLIT3 deficiency promotes lung cancer onset and progression by modulating UBE2C/WNT signaling." (PMID 39479352, 2024). "MiR-218, encoded on 4p15.31 and 5q35.1 within two host genes (SLIT2 and SLIT3), in a region of copy number loss, was selected as a priority candidate for follow-up as it is reported as underexpressed in lung cancer." (PMID 20838434, 2010). "SLIT3 is located at 5q35-q34, which is a frequent region of allelic loss in colorectal and lung cancers." (PMID 15534609, 2004). "Herein, we propose the hypothesis that abnormal SLIT3 expression may be linked to lung cancer development." (PMID 39479352, 2024). "In this study, decreased SLIT3 at the transcriptome and proteome levels was observed in lung cancer tissues." (PMID 39479352, 2024). "In the course of this investigation, the impact of SLIT3 expression on the survival of lung cancer patients was assessed." (PMID 39479352, 2024). "The current study elucidated that SLIT3 expression was downregulated in vitro lung cancer cell assays and related to poor prognosis." (PMID 39479352, 2024). "Upregulated UBE2C exerts a synergistic efficacy with downregulated SLIT3 and is crucial in lung cancer progression." (PMID 39479352, 2024). "In line with the previous study on SLITs in tumors, decreased SLIT3 was observed at the transcriptome and proteome levels in lung cancer tissues." (PMID 39479352, 2024). "Further, the data acquired in this research presented the preliminary proof for SLIT3/UBE2C/WNT signaling pathway on lung cancer development and progression, providing novel insight and strategy in clinical NSCLC treatment." (PMID 39479352, 2024). "Silencing SLIT3 expression enhanced cell proliferation and migration, indicating potential characteristics of a tumor suppressor gene of SLIT3 in non–small-cell lung cancer (NSCLC)." (PMID 39479352, 2024). "The expression of SLIT3 is downregulated in lung tumor tissues and silencing of SLIT3 in lung cancer cells induces epithelial-mesenchymal transition by downregulating E-cadherin and enhancing MMP2 and MMP9 expression." (PMID 35053460, 2022). "A second copy of miR-218 (miR-218-2) occurs within the SLIT3 locus located at 5q35.1, and expression of SLIT3 has also been shown to be down-regulated in lung cancer." (PMID 20567512, 2010). "In addition, our prior work has found that the SLIT3 gene is highly methylated, especially in advanced-stage lung cancer tissues." (PMID 39479352, 2024). "Similarly, in lung cancer, we observed downregulated SLIT3 and simultaneously upregulated WNT 3A expression, manifested by activating the WNT/β-catenin signaling pathway." (PMID 39479352, 2024). "Herein, we propose the hypothesis that abnormal SLIT3 expression may relate to lung cancer development based on our previous findings." (PMID 39479352, 2024). "However, it has not been reported in lung cancer yet, although hypermethylation of SLIT2 and SLIT3 has been reported in lung cancer." (PMID 35053460, 2022). "Meanwhile, both SBK1 and SLIT3 were found to play a vital role in lung cancer by miRNA or lncRNA." (PMID 35090416, 2022). "Nevertheless, we suggested that BIRC5, FGF2, RTKN2 and SLIT3 may be important for lung cancer; but experiment verification should be performed in future." (PMID 32299382, 2020). "Therefore, the function of SLIT3 was further investigated in lung cancer." (PMID 39479352, 2024). "SLIT3 had tumour suppressor activity, which was frequently methylated and inactivated in BRCA, as well as in cervical cancer, lung cancer and colorectal cancer." (PMID 40778650, 2025). "The roles of SLIT3 and UBE2C in the development and progression of lung cancer are still controversial." (PMID 39479352, 2024). "SLIT3 was also induced by a DNA methylation inhibitor, and silencing of SLIT3 promoted proliferation, migration, and invasion with enhanced expression of MMP2 and MMP9 in lung cancer cells." (PMID 30613364, 2018).
lung carcinoma (continued). "In order to correlate our findings with lung cancer prognosis in clinical settings, we analyzed the data from 1405 lung cancer patients and the gene expression of miR-218 host genes (SLIT2/SLIT3), IL-6, IL-6R, JAK3 and STAT3 in their tumor tissues." (PMID 28830450, 2017). "For example, altered epigenetic control of SLIT2 and SLIT3 has also been reported in lung cancer with hypermethylation of SLIT2 and to a lesser extent SLIT3." (PMID 20838434, 2010). "Furthermore, the possible mechanisms by which SLIT3 might regulate lung cancer development by influencing the UBE2C expression and activating the Wnt signaling pathway activation in lung cancer cell lines were examined." (PMID 39479352, 2024). "However, the function of SLIT3 in lung cancer is not well established yet." (PMID 39479352, 2024).
thyroid cancer (8 papers, 2014 to 2022). "Metylation inactivation of tumor suppressor SLIT3 was responsible for invasion of thyroid cancer cells, but silencing this gene may be associated with invasion of EOC." (PMID 30970615, 2019). "Hypermethylation and down-regulation of Slit3 has been reported in several types of cancers such as thyroid cancer, colorectal cancer, gastric cancer, nasopharyngeal carcinoma, cervical cancer, ovarian cancer and pancreatic ductal adenocarcinoma." (PMID 29859044, 2018). "Meanwhile, the synergistic inhibitory effects of mir-218-2 and SLIT3 have been detected in thyroid cancer cell invasion and proliferation." (PMID 27974673, 2017). "Other recent studies have validated mir-218-2 and its host gene SLIT3 as being concomitantly downregulated in thyroid cancer." (PMID 27974673, 2017). "SLIT3 has rarely been reported in human cancers, which could inhibit the progression of thyroid cancer." (PMID 36185284, 2022). "SLIT3 has anticancer effects in thyroid cancer, hepatocellular carcinoma, and melanoma." (PMID 35996510, 2022). "In conjunction, hypermethylation and subsequent down-regulation of Slit3 has been reported in several cancers, including thyroid cancer, colorectal cancer, gastric cancer, nasopharyngeal carcinoma, cervical cancer, ovarian cancer and pancreatic ductal adenocarcinoma." (PMID 29859044, 2018). "However, in gastric cancer and thyroid cancer, it was shown that down-regulation of miR-218 was attributed to low expression levels of SLIT3, and restoring the expression of miR-218-2 and SLIT3 could repress cell invasion and migration." (PMID 24705471, 2014). "SLIT3 was involved in the final model, and previous researches had demonstrated that the suppression of SLIT3 might induce tumor proliferation and invasion in many solid tumors such as ovarian cancer, hepatocellular carcinoma, thyroid cancer, and gastric cancer." (PMID 36059555, 2022).
colorectal cancer (7 papers, 2004 to 2025). A primary or metastatic malignant neoplasm that affects the colon or rectum. "Further investigation into the genomic location of miR-218-5p, embedded within the SLIT2 and SLIT3 introns on chromosome 4 and chromosome 5, respectively, revealed epigenetic silencing through promoter hypermethylation in colorectal cancer cell models." (PMID 40362385, 2025). "cfDNA samples were obtained from xenografted mice that were inoculated with one of two human colorectal cancer cell lines, SW620 and SNU407, which were analyzed for the methylation status of THBD and SLIT3 using a MethyLight assay." (PMID 33396258, 2020).
cervical cancer (6 papers, 2011 to 2025). A primary or metastatic malignant neoplasm involving the cervix. "While UNC5 expression in cervical neoplastic tissue is still poorly studied, SLIT2 and SLIT3 have been described to be frequently inactivated (due to DNA methylation or deletion) in invasive cervical cancer, with the frequency showing gradual increase as stage progresses." (PMID 32899940, 2020). "Hypermethylation at the promoters of genes (SLIT1, SLIT2, SLIT3, ROBO1, and ROBO3) involved in Slit-Robo pathway resulting in down-regulated gene expression was also indentified in invasive cervical cancer." (PMID 22140553, 2011).
major depressive disorder (5 papers, 2010 to 2022). An episode of depression lasting two or more weeks without an intervening episode of mania. "A subset of these genes has been implicated in other neurobehavioral disorders including depression (SLIT3), epilepsy (CLCN2, PRICKLE1), intellectual disability (AP4M1), schizophrenia (WDR60), and Tourette syndrome (OFCC1)." (PMID 24410847, 2014). "In line with this notion, it has been reported that SLIT3 mutations are associated with schizophrenia and major depressive disorder, which may be attributed to the overlapped genetic susceptibility between ASD and other neuropsychiatric disorders." (PMID 30483073, 2018). "Previous studies have found functional changes in SLIT3 genes to be associated with depression." (PMID 30483073, 2018). "For example, duplications of the SLIT3 locus were observed in major depressive disorder cases, and families carrying an alteration in SLIT3 presented with a history of depression." (PMID 30483073, 2018).
melanoma (5 papers, 2016 to 2022). A malignant, usually aggressive tumor composed of atypical, neoplastic melanocytes. "Nevertheless, the association between SLIT3 mutations and reduced disease free survival suggests that SLIT3 might play an important role in melanoma." (PMID 27095580, 2016). "SLIT3 is important in regulating the FBs activity and collagen synthesis in an autocrine manner, is involved in cell migration and tumor suppression, is shown to be low in lung tumor tissue; however, treatment by SLIT3 inhibits the proliferation of malignant melanoma cells." (PMID 34572749, 2021). "In agreement with a previous study showing the inhibitory role of SLIT3 in melanoma cell migration, we can hypothesis that SLIT3 acts as tumor suppressor in melanoma." (PMID 27095580, 2016). "In the turquoise module, the hub genes Cxcl14 and Slit3 are known to inhibit EMT by suppressing respectively the NF-κB and Robo signaling pathways; they were shown to reduce cell migration in melanoma." (PMID 32831131, 2020).
glioma (4 papers, 2004 to 2022). A benign or malignant brain and spinal cord tumor that arises from glial cells (astrocytes, oligodendrocytes, ependymal cells). "In primary tumours, SLIT3 was methylated in 16% of primary breast tumours, 35% of gliomas and 38% of colorectal tumours." (PMID 15534609, 2004). "SLIT3 5′ CpG island was also hypermethylated in 12 out of 32 (37.5%) colorectal tumours and in 21 out of 60 (35%) glioma primary tumours." (PMID 15534609, 2004). "SLIT3 was found to be methylated in 12 out of 29 (41%) of breast, one out of 15 (6.7%) lung, two out of six (33%) colorectal and in two out of (29%) glioma tumour cell lines." (PMID 15534609, 2004). "Therefore, the miRNA network upstream of SLIT1 and other possible miR-640 targets (e.g., SLIT2 and SLIT3 mRNAs) related to glioma radiation resistance requires further exploration." (PMID 35996510, 2022). "Accordingly, we hypothesize that mir-218-2, together with its host gene SLIT3, contribute to glioma tumorigenesis." (PMID 27974673, 2017). "In addition, SLIT3 interacts with Robo4 to induce tumor angiogenesis, SLIT3 is a glycoprotein that guide axonal development during embryogenesis and cell migration that is frequently hypermethylated and silenced in lung, breast, colorectal and glioma cell lines and primary tumors." (PMID 27355345, 2016).
lung adenocarcinoma (4 papers, 2017 to 2024). A carcinoma that arises from the lung and is characterized by the presence of malignant glandular epithelial cells. "The data revealed that the levels of SLIT2 and SLIT3 were also significantly lower with fold change of SLIT2 to be 0.14 (p = 1.3 × 10−15) in lung adenocarcinoma tissues when compared to normal lung tissues." (PMID 28830450, 2017).
Obesity (4 papers, 2009 to 2025). Accumulation of substantial excess body fat. "SLIT3 (slit guidance ligand 3) variants associated with inflammation and obesity showed an increase of Clostridiaceae and Dermococcus spp." (PMID 40452061, 2025). "Pyrosequencing results validated the association of SETD8, SLIT3, and RPTOR methylation with GWG and showed that higher levels of SETD8 and RPTOR methylation and lower levels of SLIT3 methylation relate to a higher risk of obesity in the offspring." (PMID 37513594, 2023). "Conversely, offspring with increased methylation of SLIT3 had a lower risk of obesity, including lower BMI-SDS, FM-SDS, and ΔBW–BMI (all p < 0.05)." (PMID 37513594, 2023). "In the offspring, SETD8 and SLIT3 expression levels were associated with obesity risk factors at age 6, in opposite directions as compared with their methylation levels." (PMID 37513594, 2023). "Obesity has consistently been linked to an inflammatory state, and taken together, these results evoke a possible function of SLIT3 in obesity developmental mechanisms." (PMID 37513594, 2023). "We investigated whether variants in CTNNBL1 (including rs6013029) and in three other genes (SH3PXD2B, SLIT3 and FLJ42133,) were associated with obesity." (PMID 19228371, 2009).
osteoporosis (4 papers, 2005 to 2023). A condition of reduced bone mass, with decreased cortical thickness and a decrease in the number and size of the trabeculae of cancellous bone (but normal chemical composition), resulting in increased fracture incidence. "Recently, the SNP rs10036727 in the SLIT3 gene was reported to be associated with osteoporosis at the femoral neck in postmenopausal women, supporting the notion of a protective role of SLIT3 in bone metabolism." (PMID 37596575, 2023). "Another study implicated a role for another osteoblast-derived proangiogenic factor slit homolog 3 protein (SLIT3) in osteoporosis-associated loss of bone mass and vasculature." (PMID 33324652, 2020). "By searching for references in PubMed we discovered that 9 of these genes (~ 15% of the total) are already candidates for involvement in diseases including Alzheimers (ABCA2), osteoporosis (COL4A1 and COL4A2) and schizophrenia (SLIT3)." (PMID 15766383, 2005).
ovarian carcinoma (4 papers, 2011 to 2022). A malignant neoplasm originating from the surface ovarian epithelium. "Basal SLIT2, SLIT3, ROBO1, ROBO2 and ROBO4 expression was lower in primary cultures of ovarian cancer epithelial cells when compared to normal OSE (P<0.05) and in poorly differentiated SKOV-3 cells compared to the more differentiated PEO-14 cells (P<0.05)." (PMID 22132142, 2011).